KRAS (KRas proto-oncogene, GTPase)
Diseases named in the same sentence as KRAS in open-access papers (continued):
Sharing a sentence is not in itself a finding about the gene and the disease.
tumor (continued). "Therefore, anti-EGFR monoclonal antibodies are only indicated in patients with KRAS wild-type tumours." (PMID 24720724, 2014). "Previously untreated patients with wild-type KRAS tumours received biweekly cetuximab (500 mg/m2 on day 1) plus FOLFOX-4 (oxaliplatin 85 mg/m2 on day 1, leucovorin 200 mg/m2 on days 1 and 2, and fluorouracil as a 400 mg/m2 bolus followed by a 22-hour 600 mg/m2 infusion on day 1 and 2)." (PMID 25417182, 2014). "The possible reason for this finding is that the mutation site of these codons cannot activate KRAS, which may explain the discordance in KRAS status between tumor and blood samples." (PMID 24884535, 2014). "In conclusion, the results from this prospective study provide further support to the accumulating evidence of the influence of lifestyle factors and sex on different pathways of colorectal carcinogenesis, defined by KRAS and BRAF mutation status of the tumours." (PMID 24918610, 2014). "None of the KRAS effector domain mutants were capable of causing tumor formation on their own, and KRASV12 expression led to tumor formation in only two wild-type mice out of eight." (PMID 24489653, 2014). "Mutations in KRAS and BRAF are mutually exclusive, but KRAS and PIK3CA mutations may coexist within the same tumor." (PMID 25361007, 2014). "The median ages of patients whose tumor tissue contained mutations of KRAS, PIK3CA and NRAS (54.5, 58.0 and 56.0 years, respectively) were lower than that of patients containing all-wild types of KRAS, BRAF, PIK3CA and NRAS (median age, 64.0 years)." (PMID 24774510, 2014). "Like HER2 amplification and KRAS mutations, rare MET-amplified cells were found in pretreatment tumor material from one out of three patients with MET-driven acquired resistance, suggesting that preexisting clones were selected under the pressure of anti-EGFR therapy." (PMID 24811491, 2014). "Neither the tumor site nor the KRAS mutation status were found to influence the likelihood of liver (P = 0.160) or lung (P = 0.579) metastasis." (PMID 29147353, 2013). "While BxPC-3 (KRAS wild type) and MIA PaCa-2 (KRAS mutated) cell lines were sensitive to GDC0941 and AZD6244 as single agents, synergistic inhibition of tumor cell growth and induction of apoptosis were observed in both cell lines when the two drugs were combined." (PMID 24130864, 2013). "In the multivariate logistic regression analysis, we selected sex, age, primary tumor site, tumor differentiation, tumor stage and distant metastasis as covariates, and KRAS mutants appeared more frequently in patients older than 60 (P = 0.023), as well in female patients (P = 0.016)." (PMID 24339949, 2013). "In 2009, the FDA updated the product labels for cetuximab and panitumumab, indicating that patients with CRC tumours harbouring KRAS mutations were unlikely to derive benefit from these therapies." (PMID 23356214, 2013). "In CRC, constitutively active KRAS mutation has been found to render tumor cells independent of EGFR signaling and thereby resistant to EGFR-targeted therapies." (PMID 23355875, 2013). "The present study reports an additional case of an advanced adenocarcinoma of the colon showing two somatic mutations (p.G12D and p.G12V) in the same codon (codon 12) of exon 2 of the KRAS gene, thus supporting the possibility of two differing clonal origins of the tumor." (PMID 23761841, 2013). "Moreover, our results also demonstrated a close correlation between KRAS overexpression and unfavorable clinicopathological factors, including larger tumor size, lymph node metastasis, advanced UICC stage and the presence of nerve invasion." (PMID 23425895, 2013). "In the present study, the KRAS status was investigated only in the primary tumor specimens." (PMID 29147353, 2013). "Taken together, the simultaneous activation of GNAS- and KRAS–dependent pathways might cooperatively promote tumor genesis in various gastrointestinal organs." (PMID 24312577, 2013).
tumor (continued). "We combined tumour mutation data from the Cancer Genome Atlas with matched patient genetic data, and tested for germline variants that associate with somatic mutation of the EGFR pathway (including EGFR, KRAS, BRAF, PTEN and PIK3CA)." (PMID 24152305, 2013). "Several lines of evidence suggest that not only the presence or absence of a KRAS mutation but its molecular nature influences tumour cell behaviour." (PMID 23506169, 2013). "Previously published data showed that a considerable fraction of colorectal lymph node metastases do not resemble the primary tumor in terms of KRAS mutation status." (PMID 24304820, 2013). "KRAS genotyping using tumor samples was analyzed by Luminex® assay." (PMID 24304820, 2013). "When the KRAS mutant tumor cells were minority, most of KRAS wild-type tumor cells could also be killed by EGFR antibody treatment and in this process cancer patients could show a relatively long time of stable disease or even partial response." (PMID 23874486, 2013). "From June 10, 2008, in response to new data, the trial was amended to a prospectively stratified design, restricting panitumumab randomisation to patients with KRAS wild-type tumours; the results of the comparison between the irinotcan and IrPan groups are reported here." (PMID 23725851, 2013). "The genetics for these tumor sub-types are not yet completely understood as some groups have found that disc tumors have increased nuclear β-catenin and no KRAS or BRAF mutations, while other groups have found the opposite." (PMID 23638973, 2013). "They concluded that subclonal populations harbouring KRAS mutations existed before commencing treatment, and that under the selective pressure of anti-EGFR blockade, resistant subclones rapidly expand and repopulate the tumour." (PMID 23664091, 2013). "KRAS is one of the most frequently activated oncogenes found in about 17–25% of tumor cells." (PMID 23967198, 2013). "In KRAS wild type cases, the median survival was 37 months for EREG-high as compared to 23 months for EREG-low expressing tumours (p=0.01), while in KRAS mutated tumours median survival was 33 versus 19 months (p=0.02) in EREG-high vs. low cases." (PMID 23374602, 2013). "Immunohistochemical staining for MAPK was not sufficiently sensitive, nor specific, to precisely predict the KRAS mutational status of the tumor." (PMID 23388101, 2013). "KRAS mutations were observed in only one sample and no tumor was found to harbor a BRAF V600E point mutation." (PMID 23637996, 2013). "The previously reported lower concordance levels of KRAS between the primary tumor and metastases are likely due to bias arising from false-negative results in underpowered studies and the correct evaluation of the amount of tumor tissue in the sample, or the sensitivity of the testing method used." (PMID 24304820, 2013). "Similarly, KRAS protein expression detected by western blot analysis demonstrated a marked increase in tumor tissues compared to peritumoral tissues." (PMID 23425895, 2013). "The resected tumor specimen showed the presence of wild-type KRAS." (PMID 24304820, 2013). "Somewhat surprisingly, these selection criteria resulted in patients whose tumours were KRAS wild type and thus who might reasonably be expected to respond to cetuximab being excluded from the analysis." (PMID 23286345, 2013). "In 6 patients for whom sufficient pre-treatment tumor samples were available for high-coverage 454 sequence analyses or beads, emulsion, amplification and magnetics, KRAS mutations were found to be absent." (PMID 24304820, 2013). "Survival analysis stratified by clinical stage revealed that KRAS-mutation was associated with a favourable prognosis in tumours being in a less advanced, FIGO I-II, clinical stage, but not in FIGO Stage III-IV tumours, irrespective of histological subtype." (PMID 23800114, 2013).
tumor (continued). "Presence of KRAS mutations tended to shorten survival of patients in general (n = 150; P = 0.07) and in all studied sub-categories (except tumor stage T4), however without reaching statistical significance." (PMID 23565280, 2013). "In disagreement with the literature, the present study did not identify an association between KRAS mutation status and the primary tumor site (colon or rectum) or the localization of the lung and liver metastases." (PMID 29147353, 2013). "Other clinicopathological factors, such as gender, histology, Dukes stage, tumor size, pathological type, and location of the tumor showed no positive relationship with KRAS mutations." (PMID 23355875, 2013). "Furthermore, they summarised literature that reported patients with KRAS mutant tumours who still responded to cetuximab." (PMID 23286345, 2013). "Since tumor had great heterogeneity, different tumor tissues may also have variable abundance of KRAS mutant tumor cells." (PMID 23874486, 2013). "In combination with the results of gene expression profiling of these two tumor types, activation of oncogenic KRAS and PI3K survival pathways, and inactivation of tumor suppressor genes PTEN and ARID1A are suggested for clear cell and endometrioid ovarian carcinomas, respectively." (PMID 23466883, 2013). "KRAS mutations in the surgically negative resected margins have also been shown to be associated with clinical cancer recurrence, aggressive tumor biology and poor survival." (PMID 23565280, 2013). "Tumor malignancy depends not on the presence of a KRAS mutation but on the molecular configuration and constituent mutation type." (PMID 23565280, 2013). "The aim of the trial was therefore amended: evaluation of panitumumab would now focus on patients with KRAS wild-type tumours, with quantification of treatment benefit and evaluation of further biomarkers in this selected population, rather than in an unselected population." (PMID 23725851, 2013). "Furthermore, we revealed that poor clinicopathological features and high tumor recurrence rate are significantly associated with a low expression of RBM5 and high expression of KRAS." (PMID 23425895, 2013). "We observed an MOI-dependent killer effect; the well differentiated and non-mutated KRAS, BxPc3 tumor cells were less sensitive to wtPV-H1 infection than the chemoresistant cell lines AsPc1 and Panc1." (PMID 23967078, 2013). "The real-time PCR analysis of EGFR and KRAS mutations conducted in the present study, led to identification of EGFR c.2582T>A (L861Q) and KRAS c.35G>T (G12V), detected in 1,000–5,000 and 100–1,000 tumor cells, respectively." (PMID 23817662, 2013). "However in our study, among patients with KRAS wild-type tumours, the impact of high AURKA-CN level was most pronounced in patients who did not receive cetuximab." (PMID 22240781, 2012). "Furthermore, when the analysis was conducted based on the KRAS status of primary tumor, the result of our study was also the same as above." (PMID 22876814, 2012). "The benefit of treatment with bevacizumab appears to be greater in patients with WT KRAS tumours." (PMID 23174912, 2012). "As it turned out, they are only effective on tumors with a wild-type KRAS gene, but in patients with a KRAS mutated tumor, the drug even has a negative effect." (PMID 22358180, 2012). "Similarly to PFS, the longer OS for patients with high AURKA-CN tumours was particularly pronounced in the KRAS wild-type patient population." (PMID 22240781, 2012). "Other tumor markers that play an important role in lung carcinogenesis and are implicated in the treatment response of NSCLC patients should also be evaluated, namely cyclin D1, kRAS and EGFR (epidermal growth factor receptor)." (PMID 22701665, 2012). "Considering the genetic heterogeneity of CRCs, the absence of detectable KRAS mutations in primary tumour tissue samples does not exclude the presence of KRAS mutations in metastatic tissues." (PMID 23226727, 2012).
tumor (continued). "The presence of a KRAS mutation, however, was not indicative of tumor regression after preoperative chemoradiotherapy." (PMID 22382702, 2012). "The tumor from one patient harbored no less than four detected mutations (KRAS p.G12S, one PIK3CA exon 9 mutation, and two PIK3CA exon 20 mutations)." (PMID 23226389, 2012). "We found that the association of disease-free survival with ATM expression is independent of tumour stage, location, use of chemo/radiotherapy, gender, KRAS/BRAF mutation status, microsatellite instability or chromosomal instability." (PMID 23154512, 2012). "Similarly, 6% (60 of 999) of tumor samples in the CRYSTAL study had a BRAF mutation, mainly in the setting of wild-type KRAS." (PMID 23202889, 2012). "Later lines of therapy might influence OS, but response rates and PFS, which are not influenced by second- and third-line therapy, were also better in patients with WT KRAS tumours and may be a more appropriate marker for the success of treatment than OS." (PMID 23174912, 2012). "The genetic profile of a tumor determines its biological behavior and the EGFR and KRAS mutation status could very well influence the pattern of metastasis formation, a topic that merits further investigation." (PMID 22528563, 2012). "No patients with wildtype KRAS or BRAF tumor tissue genotypes had mutations in their respective cpDNA." (PMID 23144797, 2012). "Patients with mCRC should have their tumor checked for BRAF mutation if they do not have KRAS mutation, to see if they are eligible for clinical trials for BRAF mutation inhibitors or drugs targeting the MAPK pathway." (PMID 22792460, 2012). "Similarly, other studies have identified KRAS as a target of several miRNAs down-regulated in tumors (let-7, miR-96 and miR-143), that also have an effect on cancer cell proliferation and tumor invasiveness." (PMID 22701724, 2012). "We conducted a univariate analysis of survival for different patient characteristics, including age, gender, race, tumor type (mucinous vs. not), Duke's stage at diagnosis, site of primary tumor, KRAS, BRAF and PIK3CA mutations." (PMID 22675430, 2012). "CDKN2A methylation positivity was associated with MSI (p = 0.025), BRAF mutation (p < 0.0001), higher tumor grade (p < 0.0001), mucinous histology (p = 0.0209) but not with KRAS mutation." (PMID 22925370, 2012). "Unsupervised clustering analysis of the resulting phosphorylation of 102 array substrates defined two tumor classes, both consisting of cases with and without KRAS/BRAF mutations." (PMID 23226389, 2012). "Similarly, a recent trial of first-line treatment with cetuximab in combination with FOLFIRI showed that such treatment reduced the risk of disease progression compared with FOLFIRI alone in patients with KRAS wild-type tumours." (PMID 21848897, 2012). "Our observation that KRAS/BRAF wild-type and mutated tumors had overlapping kinase activity profiles is consistent with the increasing recognition of tumor heterogeneity, reflected in disparate mutation status, as determinant of variable response to anti-EGFR antibody therapy." (PMID 23226389, 2012). "In an established tumour, modulation of KRAS by miR-143 may be differentially regulated which could possibly explain our findings." (PMID 22804917, 2012). "By comparison of normal and tumor expression of KRAS mRNA and protein at a ratio of 2.0 as a cutoff point, we found that expression of KRAS mRNA and protein was significantly increased in NSCLC compared the non-tumor tissues (P = 0.03 and P = 0.018, respectively)." (PMID 22537942, 2012). "In a study of 95 tumour biopsies from squamous cell anal cancers, the tumours lacked the common KRAS and EGFR mutations." (PMID 22619735, 2012). "It is most likely that a small, undetectable population of KRAS mutant cells was present in the patients tumor at the time of surgical resection and that the growth advantage conferred by KRAS activation allowed for subsequent expansion of KRAS mutant cells during early PDCCE passages." (PMID 22675560, 2012).
tumor (continued). "However, after division by KRAS status, the patients with low EREG expression in the primary tumor had significantly better overall survival than those with high expression in the KRAS wild-type group (p = 0.018, median survival time: 2222 days vs. 1190 days)." (PMID 22409860, 2012). "Mean (SE) change from baseline in health state index score in responding patients with WT KRAS tumours were positive throughout the study: +0.05 (0.03), +0.07 (0.03), +0.05 (0.03), +0.02 (0.03), +0.05 (0.04) at weeks 8, 16, 24, 32 and safety follow-up visit, respectively." (PMID 23020584, 2012). "Moreover, NVP-BEZ235 was able to show anti-tumor efficacy in vitro and in vivo and also increase radiosensitivity in KRAS-mutant NSCLC cell lines." (PMID 24281308, 2012). "On the other hand, the prevalence of the KRAS variant was not statistically significantly different in regards to what percent of the tumor formed normal duct structures." (PMID 22436609, 2012). "Tumor specimens from 201 patients with advanced CRC from a randomized, phase III trial comparing oxaliplatin/5-FU vs. oxaliplatin/capecitabine were retrospectively analyzed for KRAS mutations." (PMID 22876876, 2012). "KRAS genotyping in metastatic CRC patients may be prevented due to the difficulty in obtaining tumour samples from certain patients." (PMID 23226727, 2012). "Whether this is a chance finding, or because patients with MT KRAS tumours have a different natural history with more aggressive disease, remains to be resolved." (PMID 23174912, 2012). "It is possible that the difference observed in OS may be a result of patients with WT KRAS tumours receiving anti-EGFR therapy after the treatment of the study." (PMID 23174912, 2012). "Previously published data showed that a considerable fraction (25%) of colorectal lymph node metastases does not resemble the primary tumour in terms of KRAS mutation status." (PMID 21364579, 2011). "KRAS and BRAF mutations were mutually exclusive except in one patient (who had a pCR and therefore further tissue was not available) in which the tumor was positive for both KRAS and BRAF mutations." (PMID 21910869, 2011). "Metastatic CRC patients with tumours harbouring a KRAS mutation are resistant to treatment with anti-EGFR antibodies, showing lower response rates, decreased progression-free survival, and overall survival compared with patients with KRAS wild-type tumours." (PMID 21364579, 2011). "However, little is known about the interrelationship between tumor-infiltrating T cells, MSI, and other molecular features of CRC, including CIMP, global DNA hypomethylation, or KRAS, BRAF and PIK3CA mutations." (PMID 24212797, 2011). "Reduced copy number and expression of NCAM1 in tumours bearing KRAS mutations, as seen in our data, has not previously been reported." (PMID 21385341, 2011). "Relationships between the presence /absence of various gene mutations and the efficacy of molecular targeted agents have been identified in various cancers; for example, the efficacy of anti-EGFR antibody was limited to colorectal cancer patients with wild-type KRAS expression in the tumor." (PMID 24212807, 2011). "With human KRAS primers that amplify tumour-derived ctDNA fragments of increasing length up to 409 bp, the highest ctDNA concentrations were obtained for amplicons of length <100 bp and were much higher than the values obtained for mouse (non-tumoral and control) ctDNA." (PMID 21909401, 2011). "KRAS mutation analysis is usually performed on primary tumour tissue because metastatic tissue is often not available." (PMID 21364579, 2011). "We conclude that EBUS-TBNA of lymph nodes infiltrated by NSCLC can provide sufficient tumour material for EGFR and KRAS mutation analysis in most patients, and that COLD-PCR and sequencing is a robust screening assay for EGFR and KRAS mutation analysis in this clinical context." (PMID 21949883, 2011).